TUBA1B (tubulin alpha 1b)
Diseases named in the same sentence as TUBA1B in open-access papers (continued):
Sharing a sentence is not in itself a finding about the gene and the disease.
cancer (26 papers, 2010 to 2025). A tumor composed of atypical neoplastic, often pleomorphic cells that invade other tissues. "To further validate these findings, we analyzed a comprehensive immunotherapy dataset, assessing the association between TUBA1B expression and clinical response across different cancers." (PMID 39968182, 2025). "Although a few studies hint at TUBA1B’s potential as a cancer diagnostic marker, its broader role in cancer biology has not been fully understood." (PMID 39968182, 2025). "Moreover, TUBA1B has been implicated in poor prognosis and chemoresistance in various cancer types." (PMID 40094001, 2025). "Despite TUBA1B’s relevance as a key microtubule isoform, its significance in cancer has been largely underexplored." (PMID 39968182, 2025). "These insights provide a valuable understanding of TUBA1B’s potential role in cancer development, progression, and immune modulation." (PMID 39968182, 2025). "In conclusion, our findings highlight TUBA1B’s potential as a prognostic biomarker and therapeutic target in human cancers." (PMID 39968182, 2025). "The observed positive correlations between TUBA1B and immunosuppressive factors and immune-regulatory genes provide insight into TUBA1B’s role in immune response interactions within cancer." (PMID 39968182, 2025). "This work not only advances understanding of microenvironment-mediated resistance but also lays the foundation for designing innovative therapeutic agents targeting the TUBA1B-microenvironment axis, ultimately improving cancer treatment outcomes." (PMID 39968182, 2025). "In this pioneering study, we analyzed TUBA1B expression and its prognostic importance across 33 cancer types, marking a first of its kind." (PMID 39968182, 2025). "We observed elevated TUBA1B levels in 28 cancers, which strongly correlated with advanced pathological stages and poorer prognoses, suggesting TUBA1B as a promising prognostic biomarker." (PMID 39968182, 2025). "To explore TUBA1B’s biological roles across cancers, we conducted a Gene Set Enrichment Analysis (GSEA) using the “clusterprofiler” package." (PMID 39968182, 2025). "To gain a comprehensive understanding of TUBA1B’s involvement in various cancers, we conducted an extensive study, examining its expression patterns, genetic alterations, and prognostic relevance." (PMID 39968182, 2025). "We not only showed that TUBA1B was overexpressed in KMT2DLOF MSI cancers compared to KMT2DWT MSI cancers in two cohorts (TCGA and POG cohorts), but we also showed that several established ICI response markers were elevated in these cases." (PMID 39578878, 2024). "Using data from TCGA, GEO, and other databases, we analyzed TUBA1B expression across various carcinoma types using transcriptional profiling, prognostic implications, genetic and epigenetic alterations, methylation patterns, and immunological significance." (PMID 38589634, 2024). "Nevertheless, a comprehensive pan-carcinoma investigation into TUBA1B, aimed at elucidating its biological role and mechanisms of action, is currently lacking." (PMID 38589634, 2024). "The downregulation of the TUBA1B gene in normal groupers reflects both the damaging effect on intestinal integrity and the potential anti-fatty liver and anti-cancer effects of long-term PC supplementation." (PMID 38137937, 2023). "Overall, the role of TUBA1B in cancers is receiving increasing attention and deserves to be explored in depth to further investigate its action mechanism and potential as a prognostic marker." (PMID 35453905, 2022).
cancer (continued). "Although the relationship of TUBA1B to human cancers has been poorly documented, one previous immunohistochemical study has demonstrated that higher expression of TUBA1B was a significant predictor of overall survival in HCC patients." (PMID 32685988, 2020). "These insights underscore TUBA1B’s multifaceted role in cancer progression and immune response." (PMID 39968182, 2025). "Further investigation into TUBA1B’s mechanisms and functions in these cancer types could pave the way for targeted interventions and personalized treatments, enhancing patient outcomes." (PMID 39968182, 2025). "The analysis revealed significant upregulation of TUBA1B in 28 out of the 33 cancers studied." (PMID 39968182, 2025). "These pathways underscore TUBA1B’s regulatory role in fundamental cellular processes within cancer." (PMID 39968182, 2025). "Thus, this study aimed to thoroughly examine TUBA1B’s expression, prognostic value, biological functions, and immunological implications in human cancers." (PMID 39968182, 2025). "These genes play vital roles in immune checkpoint regulation and cancer cell immune evasion, suggesting that TUBA1B may impact immunosuppressive factor expression." (PMID 39968182, 2025). "Through mapping cancer type-specific in silico KMT2D GI networks, we revealed several SL candidates, namely NDUFB4, MDM2, TUBA1B, and WRN, that encode targets of existing and in-development therapeutics, making them potentially viable drug targets in cancers harbouring KMT2DLOF alterations." (PMID 39578878, 2024). "We identified three priority class A candidates—namely the SL interactors MDM2, TUBA1B (COAD/READ), and NDUFB5 (STAD) and the AL interactor CDK6 (in the pan-cancer dataset)—that encode targets of approved anticancer drugs or that are the focus of drug development efforts." (PMID 39578878, 2024). "Moreover, the protein product of TUBA1B is the main component of microtubules, which is involved in cell movement and intracellular trafficking, and affects cancer prognosis." (PMID 36408734, 2023). "Notably, we also found a cluster of cells that exhibited higher expression of a set of cell cycle-related genes (CENPF, NUSAP1, PTTG1, STMN1, TOP2A, and TUBA1B), which was consistent with proliferative CAFs (pCAFs) in a previous pan-cancer study of CAFs." (PMID 37833788, 2023). "Furthermore, we explored the Cancer Drug Sensitivity Genomics (GDSC) database, integrating IC50 values for 265 small molecule drugs with mRNA expression data from 860 cell lines, to identify potential antitumor drugs associated with TUBA1B expression." (PMID 39968182, 2025). "Furthermore, results from the in silico GI screens identified several SL candidates—namely NDUFB5 (in the STAD screen), MDM2 and TUBA1B (in the COAD/READ screen), and WRN (in the pan-cancer and COAD/READ screens)—which encode proteins that can be inhibited using existing and in-development drugs." (PMID 39578878, 2024). "Thus, the overexpression of TUBA1B in QDLS syndrome might be involved in the proliferation of cancer cells." (PMID 34838074, 2021). "In this study, we examined the relationship between TUBA1B expression and TMB/MSI across seven cancer types." (PMID 39968182, 2025). "We highlighted cancer type-specific genetic interactors, namely NDUFB5, MDM2, TUBA1B, and WRN, which were promising targets of existing and in-development drugs." (PMID 39578878, 2024). "TUBA1C (r was range from 0.29 to 0.66), TUBA1B (0.21~0.65), P4HA1 (0.25~0.74), HSPA8 (0.17~0.60), CCNB1 (0.22~0.62) as the top five genes were highly correlated with glycolysis score across cancers." (PMID 32635458, 2020). "Some other genes differentially expressed in this pool of cells CD133+ and also involved in cancer and neurological disease are RPS4X, RPS3A or TUBA1B." (PMID 20735813, 2010).
cancer (continued). "This analysis revealed that TUBA1B is involved in cell cycle pathways, including “Cell Cycle,” “Signaling by Rho GTPases, Miro GTPases, and RHOBTB3,” and “Vesicle-mediated transport,” all found across nine cancer types." (PMID 39968182, 2025). "Similarly, the expression of SLC3A2, TUBA1B, TUBA1C, TUBB, FSTL1, and INSIG1 was affected by FIRΔexon2, suggesting that FIR and FIRΔexon2 engage in the transcription of various cancer-related mRNAs." (PMID 38139171, 2023). "In addition, MTlo cancer cells expressed higher levels of SMTN1, TUBB, TUBA1A, and TUBA1B genes involved in microtubule turnover which contributes to cellular processes such as intracellular transport, cell division and migration, than MThi cancer cells did." (PMID 34483138, 2021). "Additionally, we found that TUBA1B+ TAMs, C1QC+ TAMs and IL1B+ TAMs were predominant in early-stage tumors, whereas VCAN+ TAMs, SLC40A1+ TAMs and APOC1+ TAMs had higher proportions in patients with advanced cancer." (PMID 39232806, 2024). "Moreover, TUBA1B was coexpressed with almost all chemokine, chemokine receptor, MHC, immunoinhibitory and immunostimulatory genes in LIHC, and it was also highly correlated with immune-related genes in many other cancers." (PMID 35453905, 2022). "However, a comprehensive pan-cancer analysis of TUBA1B is still lacking." (PMID 39968182, 2025).
infection (3 papers, 2022 to 2025). The state of being infected such as from the introduction of a foreign agent such as serum, vaccine, antigenic substance or organism. "Cluster 1 was more heterogenous and lacked a distinct transcriptional profile, whereas Type I IFN (Isg15, Ifi206, Ifit3, Ccl5) and proliferative signatures (Cdk1, Mki67, Tuba1b) were observed in clusters 3 and 5, respectively, whose numbers remained stable between days 7 and 14 after infection." (PMID 39989461, 2025). "In male mice, there were 478 DEGs in the infection group (MT) compared with the control group (MC); 122 genes with upregulated expression, such as Ifitm1, Wfdc21, Wfdc17, and Adam8 (P < 0.001); and 356 genes with downregulated expression, such as Tuba1b and Cox7b (P < 0.001)." (PMID 40303139, 2024).
TUBA1B also shares sentences with these, for which no sentence is quoted: colorectal (2 papers); lung squamous cell carcinoma (2); non-small cell lung carcinoma (2); prostate adenocarcinoma (2); thyroid carcinoma (2); adenocarcinoma (1); bladder urothelial carcinoma (1); brain cancer (1); breast invasive carcinoma (1); cervical cancer (1); cholangiocarcinoma (1); colon cancer (1); COVID-19 (1); Fanconi anemia (1); head and neck squamous cell carcinoma (1); legionellosis (1); Lissencephaly (1); lymphoma (1); neurological disease (1); ovarian serous cystadenocarcinoma (1); pancreatic adenocarcinoma (1); pancreatic cancer (1); postmenopausal osteoporosis (1); prion disease (1); prostate carcinoma (1); renal cell carcinoma (1); schizophrenia (1); stomach adenocarcinoma (1); Stroke (1); systemic lupus erythematosus (1).
A further 2 diseases each share a sentence with TUBA1B in 1 paper.